AAK1 (AP2 associated kinase 1)
Description:
Regulates clathrin-mediated endocytosis by phosphorylating the AP2M1/mu2 subunit of the adaptor protein complex 2 (AP-2) which ensures high affinity binding of AP-2 to cargo membrane proteins during the initial stages of endocytosis. Isoform 1 and isoform 2 display similar levels of kinase activity towards AP2M1. Preferentially, may phosphorylate substrates on threonine residues. Regulates phosphorylation of other AP-2 subunits as well as AP-2 localization and AP-2-mediated internalization of ligand complexes. Phosphorylates NUMB and regulates its cellular localization, promoting NUMB localization to endosomes. Binds to and stabilizes the activated form of NOTCH1, increases its localization in endosomes and regulates its transcriptional activity. (Microbial infection) By regulating clathrin-mediated endocytosis, AAK1 plays a role in the entry of hepatitis C virus as well as for the lifecycle of other viruses such as Ebola and Dengue.
Synonyms: KIAA1048; DKFZp686K16132
Tractability: Small molecule: a structure with a bound ligand is known; a high-quality ligand is known; it belongs to a druggable protein family. Antibody: its Gene Ontology location is reachable by antibodies, with high confidence; UniProt places it where antibodies can reach, with medium confidence; the Human Protein Atlas places it where antibodies can reach. PROTAC: it is named in the literature on targeted protein degradation; ubiquitination databases record sites on it; its protein half-life has been measured; a small molecule that binds it is known.
Target class: Protein Kinase; Other protein kinase NAK family; Other protein kinase group; Enzyme; Kinase
Chemical probes: LP-935509 (high quality), SGC-AAK1-1 (high quality), SGC-CDKL2/AAK1/BMP2K-1 (high quality)
Gene: Protein-coding gene on chromosome 2 (69,457,997 to 69,674,349, reverse strand). Ensembl gene ENSG00000115977.
Subcellular location: Cell membrane; Membrane, clathrin-coated pit; Presynapse
Subcellular location (Human Protein Atlas): Plasma membrane; Cytosol; Vesicles
Pathways (Reactome):
Vesicle-mediated transport: Cargo recognition for clathrin-mediated endocytosis; Clathrin-mediated endocytosis
Gene Ontology:
Molecular function: AP-2 adaptor complex binding; Notch binding; protein binding; protein serine/threonine kinase activity; ATP binding; protein kinase activity; protein serine kinase activity
Biological process: positive regulation of Notch signaling pathway; protein phosphorylation; protein stabilization; regulation of clathrin-dependent endocytosis; regulation of protein localization; membrane organization
Cellular component: plasma membrane; cell leading edge; clathrin-coated pit; clathrin-coated vesicle; cytosol; presynapse; terminal bouton
Genetic constraint (gnomAD): Loss-of-function variants: 28 observed, 94.55 expected, observed/expected ratio (o/e) 0.3, 90% interval 0.22 to 0.41. The upper end of that interval is the gene's LOEUF score, 0.41, which puts it in group 1 of 6, group 1 being the genes least tolerant of losing a copy. Missense variants: 877 observed, 1,124.6 expected, observed/expected ratio (o/e) 0.78, 90% interval 0.74 to 0.82. Synonymous variants: 437 observed, 429.57 expected, observed/expected ratio (o/e) 1.02, 90% interval 0.94 to 1.1.
Homologues: Orthologues: chimpanzee AAK1 (99% identical), rabbit AAK1 (94% identical), pig AAK1 (93% identical), guinea pig AAK1 (93% identical), rat Aak1 (89% identical), mouse Aak1 (89% identical), macaque AAK1 (86% identical), dog AAK1 (83% identical), tropical clawed frog aak1 (68% identical), zebrafish aak1b (55% identical), zebrafish aak1a (52% identical). Paralogues in human: BMP2K (40% identical), STK16 (10% identical).
Diseases named in the same sentence as AAK1 in open-access papers:
AAK1 is named in the same sentence as 53 diseases in open-access papers, as found by Europe PMC text mining. Sharing a sentence is not in itself a finding about the gene and the disease. The quoted sentences say what the papers report.
COVID-19 (13 papers, 2020 to 2025). A disease caused by infection with severe acute respiratory syndrome coronavirus 2. "Interestingly, 008 and 039 showed robust activity in degrading GAK and AAK1 simultaneously, indicating the possible use in antiviral treatment for coronavirus disease 2019." (PMID 37196766, 2023). "Knowledge-graph-based strategies identified baricitinib, originally developed for the treatment of rheumatoid arthritis, as a candidate for treating COVID-19 by blocking JAK1, JAK2, adaptor associated kinase 1 (AAK1), and cyclin G-associated kinase." (PMID 41522213, 2025). "Until the outbreak of COVID-19 in 2019, researchers actively explored various mechanisms of antiviral treatment, and paid more attention to the anti-viral effect of AAK1 inhibitors." (PMID 37955299, 2023). "The outbreak of the COVID-19 epidemic in recent years significantly increased the awareness of AAK1 protein and contributed to the hike in publication number." (PMID 37955299, 2023). "Baricitinib, a JAK and AAK1 inhibitor, has been suggested as a possible candidate for the treatment of COVID-19, considering its relative safety and high affinity for ACE2." (PMID 33043030, 2020). "Currently, optimizing valuable hits (3,5-disubstituted pyrrolo [2,3-b] pyridines) or use of exciting medication as potent GAK and AAK1 inhibitors could be a promising approach to manage COVID-19 INFECTION." (PMID 34222852, 2021). "Therefore, JAK inhibitors may be a potential method for treating COVID-19, by disrupting AP2-associated protein kinase 1 (AAK1) signaling to interrupt the integration of the virus with host cells." (PMID 39021569, 2024). "The results showed that compared with normal subjects, the expression levels of AAK1 and TMPRSS2 in patients who had been infected with SARS-CoV-2 were significantly down-regulated, suggesting that COVID-19 patients may consume lots of AAK1 and TMPRSS2 in the advanced stage of the disease." (PMID 33195212, 2020). "The expression patterns of ACE2, AAK1, and TMPRSS2 were also evaluated in COVID-19 patients in GSE147507 to explore gene changes in the progression of the disease." (PMID 33195212, 2020). "Intervention in AAK1 catalysis has also been explored for potential therapies in the treatment of viral diseases including HCV, dengue virus and ebola virus (DEVN), bacterial sepsis, rabies virus (RABV), and COVID-19." (PMID 37955299, 2023). "GAK and AAK1 inhibitor such as baricitinib have been wished for as a potential therapeutic agent for COVID-19 treatment by decreasing the viral entry, though no investigational work has been conducted to verify its mechanism of action." (PMID 34222852, 2021). "Baricitinib, a potent AAK1 inhibitor, has been proposed as an effective therapy for COVID-19, reducing the viral entry, although no experimental work has been done to prove its mechanism of action." (PMID 34356745, 2021).
viral infection (11 papers, 2012 to 2025). "Mechanistically, baricitinib alleviates viral infection by inhibiting AP2-associated protein kinase 1 (AAK1), a known regulator of endocytosis." (PMID 34001144, 2021). "Among 378 AAK1 inhibitors, baricitinib, binding the cyclin G-associated kinase, another regulator of endocytosis, has been shown to inhibit viral infection of cells through the inhibition of AAK1." (PMID 32638628, 2020). "As a member of the NAK family, Aak1 is a significant endocytic kinase that plays an important role in viral infection, assembly, and entry by regulating clathrin-mediated endocytosis through Numb." (PMID 40259414, 2025). "In fact, AAK1 andGAK have key roles in endocytosis, whichhas motivated the study of their involvement in processes relatedto viral infection." (PMID 33970631, 2022). "AAK1 inhibitors can stop the virus from passing into cells and can be useful in preventing virus infections." (PMID 33043030, 2020). "One of the known regulators of endocytosis is the AP2-associated protein kinase 1 (AAK1); thus, AAK1 inhibitors can interrupt the passage of the virus into cells and can be helpful in preventing virus infections." (PMID 32397174, 2020). "However, 30 maintains a nanomolar affinity for AAK1 and had been widely used to study the role of AAK1 in virus infection." (PMID 37955299, 2023). "In addition to anti-inflammatory properties, baricitinib is a JAK inhibitor with potential antiviral effects, inhibiting AP2-associated kinase 1 (AAK1) and cyclin G-associated kinase (GAK) involved in SARS-CoV-2 endocytosis, i.e. viral infection of host cells." (PMID 35707401, 2022). "Notably, the endocytic-related genes Aak1, Numb, and Notch2 are key regulators of viral infection." (PMID 40259414, 2025). "Moreover,the key role of AAK1 and GAK in virus infection has been expandedto other viruses beyond HCV, such as DENV and EBOV." (PMID 33970631, 2022). "Therefore, our findings indicate that rhabdovirus infection is AAK1-dependent and implicate AAK as a novel target to inhibit viral infection." (PMID 32872567, 2020). "Conservative requirement for AAK1 and GAK across viral families may suggest that the identified inhibitors could potentially be used for treating HCV-HIV co-infection and possibly a broader spectrum of viral infections." (PMID 22916011, 2012). "Furthermore, AAK1 and GAK have not been reported to mediate a viral infection to date." (PMID 22916011, 2012).
rheumatoid arthritis (8 papers, 2020 to 2025). A chronic, systemic autoimmune disorder characterized by inflammation in the synovial membranes and articular surfaces. "Baricitinib, a Janus kinase 1/2 inhibitor approved by the FDA for the treatment of rheumatoid arthritis, was recently found to inhibit both AAK1 and GAK and used as a potential inhibitor for 2019-novel CoV acute respiratory disease." (PMID 37196766, 2023). "One of the new drugs that are in clinical development for IBD, but already approved for the treatment of rheumatoid arthritis, is Baricitinib, a selective Janus kinase (JAK1, JAK2) and AP2-associated protein kinase 1 (AAK1) inhibitor." (PMID 32714386, 2020). "In this study, baricitinib, a Janus kinase (JAK) inhibitor indicated for the treatment of rheumatoid arthritis (RA), was identified with a particularly high affinity for AAK1." (PMID 33855032, 2021). "Baricitinib has also shown to inhibit a regulator of endocytosis, the AP2-associated protein kinase 1 (AAK1), at therapeutic dosage for rheumatoid arthritis (RA); therefore, it can interrupt virus entry through receptor-mediated endocytosis." (PMID 34659200, 2021). "Additionally, NAK kinase inhibitors (AAK1 and GAK), baricitinib, used in the treatment of rheumatoid arthritis and an inhibitor of AAK1 and Janus kinase (JAK-STAT-kinase), apparently inhibits viral multiplication." (PMID 32987852, 2020). "Interestingly, the kinase inhibitor baricitinib, which is used to treat rheumatoid arthritis (RA) and inhibits the Janus kinase/signal transducers and activators of transcription (JAK/STAT), additionally blocks NAK and AAK1 kinases and exhibited anti-viral activity in COVID-19 patients." (PMID 38004113, 2023). "In addition, a recent study suggested that baricitinib, approved for treating rheumatoid arthritis, may serve as an anti-SARS-CoV-2 drug by inhibiting AAK1-regulated virus endocytosis." (PMID 35982051, 2022).
amyotrophic lateral sclerosis (4 papers, 2019 to 2024). Amyotrophic lateral sclerosis (ALS) is a neurodegenerative disease characterized by progressive muscular paralysis reflecting degeneration of motor neurons in the primary motor cortex, corticospinal tracts, brainstem and spinal cord. "A study showed that dysfunction of AAK1 led dysregulation of synaptic vesicle recycling, which was related to the pathology of amyotrophic lateral sclerosis." (PMID 36561842, 2022).
Parkinson disease (4 papers, 2018 to 2024). A progressive degenerative disorder of the central nervous system characterized by loss of dopamine producing neurons in the substantia nigra and the presence of Lewy bodies in the substantia nigra and locus coeruleus. "For instance, the gene AAK1, targeted by miR-221, miR-17-5p, miR-155, and miR-205, is involved in the immune response and implicated in the development of diseases such as Alzheimer and Parkinson in humans." (PMID 39277740, 2024). "In addition, AAK1 is associated with Parkinson's disease in a genome-wide association study." (PMID 30623173, 2018). "Aak1 plays vital roles in neuropathic pain, schizophrenia, Parkinson's disease and other neuropathic disorders (Abdel‐Magid, 2017)." (PMID 35726359, 2022).
breast carcinoma (2 papers, 2018 to 2025). "Moreover, we found that the expression of AAK1 was lower in primary tumor tissues of breast cancer than normal tissues." (PMID 41407700, 2025).
lung adenocarcinoma (2 papers, 2020 to 2024). A carcinoma that arises from the lung and is characterized by the presence of malignant glandular epithelial cells. "To explore the susceptibility factors of cancer patients, we assessed the expression of ACE2, TMPRSS2, and the endocytic regulator AAK1 in lung adenocarcinoma (LUAD) patients and explored their effects on immune infiltration." (PMID 33195212, 2020).
Sepsis (2 papers, 2022 to 2025). Sepsis is defined as life-threatening organ dysfunction caused by a dysregulated host response to infection. "AAK1, found in immune cells, impacts virus endocytosis and inflammation, playing a role in sepsis-related coagulation." (PMID 41285832, 2025). "Taken together, our findings suggest that pharmacologically targeting AAK1-mediated LPS internalization is a valuable therapeutic option for sepsis." (PMID 35982051, 2022).
bacterial sepsis (1 paper, 2022). "PHZ-OH, a new and promising inhibitor of AAK1, may facilitate the future discovery of novel agents for efficient treatment of coagulation syndrome, organ dysfunction, and death in bacterial sepsis." (PMID 35982051, 2022). "Thus, the selective inhibition effect of PHZ-OH on caspase-11 signaling may have fewer side effects, and inhibition of LPS internalization by targeting AAK1 would be a promising strategy in the treatment of bacterial sepsis." (PMID 35982051, 2022).
breast tumor (1 paper, 2025). "Taken together, these results suggest that the expression of AAK1 might be a potential tumor prognostic indicator related to the susceptibility of ferroptosis in breast tumors." (PMID 41407700, 2025). "The non-phosphorylatable mutation of AAK1 inhibits ferroptosis and consequently promotes breast tumor growth in vivo." (PMID 41407700, 2025).
cognitive decline (1 paper, 2021). "In a murine model of AD periodic variation in AAK1 expression, it is closely correlated with cognitive decline." (PMID 34938197, 2021).
cognitive disorder (1 paper, 2021). A disease affects cognitive processes. "AAK1 inhibitors have been further developed to provide valuable treatments for disorders such as neuropathic pain, AD, and other neurodegenerative diseases, indicating that AAK1 serves as a suitable biomarker of cognitive disorders, including VaD." (PMID 34938197, 2021).
colon carcinoma (1 paper, 2014). "Depletion of AAK1 resulted in RKO colon carcinoma cell loss suggested that AAK1 might have additional function in apoptosis, although the mechanism by which it did so is not known." (PMID 25514244, 2014).
dengue (1 paper, 2021). "Recently, AAK1 inhibition has been proposed for the treatment of dengue and Ebola patients in future outbreaks." (PMID 34356745, 2021).
diabetes (1 paper, 2019). "Lexicon's clinical drug development efforts, aiming for approval of SGLT1, SGLT2 and AAK1 inhibitors, continue and their success should help patients with diabetes and neuropathic pain." (PMID 31064765, 2019). "Clinical trials evaluating inhibitors of AAK1 (neuropathic pain) and SGLT1 (diabetes) are underway." (PMID 31064765, 2019).
glaucoma (1 paper, 2022). Increased pressure in the eyeball due to obstruction of the outflow of aqueous humor. "Twelve of these genes, including PTPRB, HFM1, TAF1B, AAK1, FOXD1, EHMT1, and DNTT, are associated with glaucoma topical treatments (P < 1 × 10−5)." (PMID 36450729, 2022).
gout (1 paper, 2024). A condition characterized by painful swelling of the joints, which is caused by deposition of urate crystals. "We validated a concordant direction of effect sizes of CTBP1, PPM1G, SEPT2, and KRTCAP3 for gout; SKIV2L for heart failure; and AAK1, MAPKAPK5-AS1, POLA2, RSG1, and WWP2 for hypertension." (PMID 38658550, 2024).
injury (1 paper, 2022). Damage inflicted on the body as the direct or indirect result of an external force, with or without disruption of structural continuity. "Aak1, adaptor‐associated kinase 1, has been reported to be associated with nervous‐related diseases and nerve injury." (PMID 35726359, 2022).
neuroblastoma (1 paper, 2019). Neuroblastoma (NB) is the most common solid, extracranial childhood tumor. "We also confirmed that AAK1 siRNA knock-down inhibited the infection and spread of ERA-mCherry in HEK293 cells and in the human neuroblastoma cell line SK-N-SH (SK) by 42%–49% and 27%–31%, respectively." (PMID 31905947, 2019).
pneumonia (1 paper, 2022). An acute, acute and chronic, or chronic inflammation focally or diffusely affecting the lung parenchyma, caused by an infection in one or both of the lungs (by bacteria, viruses, fungi, or mycoplasma.). "On the other hand, human targets, including many kinases, e.g., adaptor-associated kinase 1 (AAK1), cathepsin L, and the transmembrane serine protease 2 (TMPRSS2), are involved in the advancement of symptoms associated with SARS-CoV-2 infections, such as pneumonia, inflammation, and fibrosis." (PMID 36144718, 2022).
cancer (9 papers, 2012 to 2025). A tumor composed of atypical neoplastic, often pleomorphic cells that invade other tissues. "In this study, we discovered that cancer cells absorb iron from the extracellular environment through PKCβII phosphorylating AAK1." (PMID 41407700, 2025). "Results consistently demonstrated that AAK1 expression levels were significantly higher in both OV tissues as well as cancer cell lines when compared to normal tissues and cell lines." (PMID 38169546, 2024). "Sunitinib is an FDA-approved anti-cancer drug that inhibits AAK1 kinase activity by binding to AAK1 with high affinity." (PMID 31905947, 2019). "AP2-associated protein kinase 1 (AAK1) and NOS3 were related to the clathrin-mediated endocytosis and cardiovascular-cancer-respiratory pathway, respectively." (PMID 26538867, 2015). "Last, approved anti-cancer drugs that inhibit AAK1 or GAK not only disrupt core-AP2M1 binding, but also significantly inhibit HCV assembly and infectious virus production." (PMID 22916011, 2012). "Last, approved anti-cancer drugs that inhibit AAK1 or GAK, dramatically inhibited core-AP2M1 binding, HCV assembly, and infectious virus production." (PMID 22916011, 2012). "The expression of AAK1 correlates with intracellular virus abundance, suggesting that targeting overexpressed kinases, as commonly done in cancer treatment, may facilitate suppressing viral replication." (PMID 40295816, 2024). "This underscores the importance that AAK1 may also have in the treatments of cancers and other diseases." (PMID 37955299, 2023). "In this study, it is demonstrated that AAK1 silencing affects the expression of epithelial-mesenchymal plasticity (EMP) markers and greatly improves the sensitivity of cancer cells to targeted therapy." (PMID 37955299, 2023). "In cytological experiments, we found that AAK1 could promote cancer progression and glutamine metabolism via activating the Notch3 pathway in OV cells." (PMID 38169546, 2024). "ITGAM and AAK1 have not been previously reported to be related to cancer, and our study is the first to suggest that they could be used as new prognostic markers of DLBCL." (PMID 33692952, 2021). "Eventhough AAK1 and GAK are not among the cancer targets of these compounds, they are very potently bound and inhibited by sunitinib or PKC-412 and erlotinib, respectively (with Kds of binding that are lower or comparable to the major cancer targets)." (PMID 22916011, 2012).